PLAG1 (PLAG1 zinc finger)
Description:
Transcription factor whose activation results in up-regulation of target genes, such as IGFII, leading to uncontrolled cell proliferation: when overexpressed in cultured cells, higher proliferation rate and transformation are observed. Other target genes such as CRLF1, CRABP2, CRIP2, PIGF are strongly induced in cells with PLAG1 induction. Proto-oncogene whose ectopic expression can trigger the development of pleomorphic adenomas of the salivary gland and lipoblastomas. Overexpression is associated with up-regulation of IGFII, is frequently observed in hepatoblastoma, common primary liver tumor in childhood. Cooperates with CBFB-MYH11, a fusion gene important for myeloid leukemia.
Synonyms: ZNF912; PSA; SGPA; SRS4
Tractability: PROTAC: UniProt records ubiquitination sites on it.
Gene: Protein-coding gene on chromosome 8 (56,160,909 to 56,211,333, reverse strand). Ensembl gene ENSG00000181690.
Subcellular location: Nucleus
Subcellular location (Human Protein Atlas): Nuclear speckles; Nucleoplasm; Centrosome; Cytosol
Gene Ontology:
Molecular function: DNA-binding transcription activator activity, RNA polymerase II-specific; RNA polymerase II cis-regulatory region sequence-specific DNA binding; DNA-binding transcription factor activity; DNA-binding transcription factor activity, RNA polymerase II-specific; RNA polymerase II transcription regulatory region sequence-specific DNA binding
Biological process: positive regulation of transcription by RNA polymerase II; regulation of DNA-templated transcription; negative regulation of gene expression; positive regulation of gene expression; positive regulation of glial cell proliferation
Cellular component: nuclear speck; nucleoplasm; nucleus; nuclear body
Genetic constraint (gnomAD): Loss-of-function variants: 6 observed, 31.74 expected, observed/expected ratio (o/e) 0.19, 90% interval 0.1 to 0.37. The upper end of that interval is the gene's LOEUF score, 0.37, which puts it in group 1 of 6, group 1 being the genes least tolerant of losing a copy. Missense variants: 435 observed, 600.96 expected, observed/expected ratio (o/e) 0.72, 90% interval 0.67 to 0.78. Synonymous variants: 222 observed, 229.42 expected, observed/expected ratio (o/e) 0.97, 90% interval 0.87 to 1.08.
Homologues: Orthologues: chimpanzee PLAG1 (100% identical), macaque PLAG1 (99% identical), dog PLAG1 (98% identical), rabbit PLAG1 (98% identical), guinea pig PLAG1 (98% identical), pig PLAG1 (96% identical), rat Plag1 (96% identical), mouse Plag1 (95% identical), tropical clawed frog plag1 (85% identical), zebrafish plag1 (50% identical), Caenorhabditis elegans Y5F2A.4 (11% identical), Drosophila melanogaster CG12391 (11% identical), and 2 more. Paralogues in human: PLAGL2 (51% identical), PLAGL1 (43% identical), PEG3 (14% identical), ZNF518A (14% identical), REST (13% identical), ZNF274 (11% identical), ZSCAN5C (11% identical), ZNF18 (11% identical), ZSCAN5A (11% identical), ZNF518B (11% identical), ZNF770 (11% identical), ZSCAN29 (11% identical), and 17 more.
Diseases named in the same sentence as PLAG1 in open-access papers:
PLAG1 is named in the same sentence as 140 diseases in open-access papers, as found by Europe PMC text mining. Sharing a sentence is not in itself a finding about the gene and the disease. The quoted sentences say what the papers report.
lipoblastoma (33 papers, 2013 to 2025). A lipoma usually occurring in the extremities of young children (usually boys). "Fusions involving the PLAG1 gene are associated with multiple cancers and benign tumors, including lipoblastoma and the more recently described pediatric fibromyxoid soft tissue tumor." (PMID 40879223, 2025). "The majority of lipoblastoma development is underpinned by gene rearrangements in a region of chromosome 8 encoding the zinc-finger transcription factor PLAG1." (PMID 39011190, 2024). "The PLAG1 function triggers cellular proliferation and is associated with the development of lipoblastomas and pleomorphic adenomas of the salivary gland." (PMID 34684585, 2021). "The protooncogene PLAG1 (PLAG1 zinc finger) is associated with neoplasms such as lipoblastoma or pleomorphic adenoma of the salivary gland." (PMID 34684585, 2021). "PLAG1 immunohistochemistry is also a very simple and useful diagnostic tool for distinguishing lipoblastoma from liposarcoma." (PMID 26943407, 2015). "In contrast to LLT, lipoblastoma is associated with PLAG1 rearrangements." (PMID 41246635, 2025). "According to the literature, approximately 70% of lipoblastomas exhibit rearrangements of the PLAG1 gene, and up to 18% have polysomy of chromosome 8." (PMID 40151705, 2025). "This fusion is recurrent in lipoblastoma, and PLAG1 is also the most frequent fusion partner in pleomorphic adenoma (PA), a common salivary gland neoplasm that can exhibit both epithelial and mesenchymal differentiation." (PMID 40223173, 2025). "Lipoblastoma typically occurs in infants and children and often shows pleomorphic adenoma gene 1 (PLAG1) overexpression and PLAG1/HMGA2 rearrangements, with frequent cluster of differentiation 34 (CD34) and desmin expression." (PMID 41230282, 2025). "The majority of lipoblastoma development is underpinned by gene rearrangements in the zinc-finger transcription factor PLAG1." (PMID 39011190, 2024). "In four patients, fluorescence in situ hybridization (FISH) demonstrated PLAG1 rearrangements confirming the diagnosis of lipoblastoma." (PMID 37370837, 2023). "PLAG1 is a transcription factor involved in various cancers, such as lipoblastoma, hepatoblastoma, acute myeloid leukemia, uterine leiomyoma, and leiomyosarcoma." (PMID 35288483, 2022). "PLAG1 fusion gene partners described in lipoblastoma include HAS2 (8q24.13), COL1A2 (7q21.3), RAD51B (14q24.1), COL3A1 (2q32.2), RAB2A (8q12.1–q12.2), BOC (3q13.2), DDX6, KLF10, KANSL1L, ZEB2 and EF1A1." (PMID 35407546, 2022). "On the molecular level, lipoblastomas typically show a rearrangement of the chromosomal region 8q11–13, which results most commonly in a fusion of the pleomorphic adenoma gene 1 (PLAG1) with diverse partners, most commonly HAS2 (8q24.1) and COL1A2 (7q22)." (PMID 33814013, 2021). "Regarding the results of IHC for PLAG1 reported in a previous study, 8 of 10 cases of lipoblastoma were found to involve a positive expression on PLAG1 immunohistochemistry, whereas all 12 cases of liposarcoma displayed a negative PLAG1 expression." (PMID 26943407, 2015). "Approximately, 70 % of lipoblastomas exhibit PLAG1 rearrangement located at 8q12, which can result in the transcriptional upregulation of this oncogene via promoter swapping." (PMID 26943407, 2015). "The detection of PLAG1 rearrangement is used to distinguish lipoblastoma from other lipomatous tumors as well as liposarcoma." (PMID 26943407, 2015). "As the tumor was suspected to be a lipoblastoma, we performed PLAG1 immunohistochemical staining (IHC) and an assessment for PLAG1 rearrangement using fluorescence in situ hybridization (FISH) to confirm the diagnosis." (PMID 26943407, 2015). "Recently, PLAG1 rearrangement was identified to be a characteristic cytogenetic feature of lipoblastoma." (PMID 26943407, 2015).
lipoblastoma (continued). "Although the histological findings were unusual, the tumor was diagnosed as a lipoblastoma according to both PLAG1 immunohistochemistry and the presence of PLAG1 rearrangement on fluorescence in situ hybridization." (PMID 26943407, 2015). "In lipoblastomas, several chromosomal rearrangements have been described, involving the pleiomorphic adenoma gene 1 (PLAG1) oncogene." (PMID 24714847, 2014). "Based on the current state of knowledge, translocations involving PLAG1 are specific for two pathologic entities, pleomorphic adenoma and lipoblastoma." (PMID 25137137, 2014). "Oncogenic activation of PLAG1 plays a key role in the development of lipoblastomas, hepatoblastomas, chronic lymphocytic leukemia as well as in pediatric gastro-intestinal stromal tumors." (PMID 24516594, 2014). "Research focusing on the overexpression of PLAG1 due to 8q11 locus alterations in lipoblastomas could also reveal crucial information about the genetic causes of these tumors, informing the development of personalized treatment regimens." (PMID 40729232, 2025). "Indeed, 90% of lipoblastoma tumors possess cytogenetic abnormalities in PLAG1, which ultimately leads to the amplification of genes involved in hyaluronic acid and collagen synthesis." (PMID 39011190, 2024). "RAD51B has also been reported as a translocation partner for PLAG1 in lipoblastomas." (PMID 35822448, 2023). "Approximately 80% of lipoblastoma cases show aberrant PLAG1 immunohistochemical expression." (PMID 35407546, 2022). "Similarly, it has been possible to characterize the overexpression of PLAG1 related to 8q11 locus alterations in lipoblastomas." (PMID 36264345, 2022). "Notably, previous studies have shown that PLAG1 is also involved in similar gene fusions with other partner genes in lipoblastomas." (PMID 31426421, 2019). "PLAG1 is located on human chromosome 8q12 whose oncogenic activation is a crucial event in the formation of various human tumors, including pleomorphic adenomas of the salivary glands, lipoblastoma, and hepatoblastomas." (PMID 23554918, 2013). "The recent use of cytogenetics has proven useful for making the diagnosis, as translations involving the long arm of chromosome 8, particularly 8q11-13, with or without pleomorphic adenoma gene 1 (PLAG1) oncogene rearrangements, have been found to be associated with lipoblastomas." (PMID 32997268, 2020). "Lipoblastomas typically occur in infants and children, and even in older children and adult patients, positivity for PLAG1, CD34, and desmin, along with PLAG1 and HMGA2 rearrangements, aids in diagnosis." (PMID 41230282, 2025). "Molecular genetic examinations of lipoblastomas revealed rearrangements of 8q11∼q13, hyaluronic acid synthase 2 (HAS2) and collagen 1 alpha 2 (COL1A2) as well as pleomorphic adenoma gene 1 (PLAG1) amplification." (PMID 31282548, 2020). "We reasoned that were this an unusual PA rather than lipoblastoma, the epithelial and mesenchymal components would harbour the PLAG1 translocation." (PMID 40223173, 2025). "DDIT3 rearrangement and the absence of PLAG1 rearrangement help in the differential diagnosis of MLPS from extensively myxoid lipoblastoma." (PMID 35407546, 2022). "This rearrangement targets the PLAG1 gene and has been reported in 82% of lipoblastomas but only 3% of conventional lipomas and never in myxoid liposarcoma." (PMID 32997268, 2020). "The results of PLAG1 IHC, which is specific for lipoblastoma, showed positivity in the tumor cells, and the investigation of the PLAG1 rearrangement on FISH revealed positive findings (data not shown)." (PMID 26943407, 2015). "Additionally, negative results for DDIT3, CD34, desmin, and PLAG1 support the diagnosis and help exclude myxoid liposarcoma and “adult” lipoblastoma." (PMID 41230282, 2025). "However, the tumor nuclei were negative for PLAG1, which was reported to have high sensitivity and specificity for lipoblastoma." (PMID 39109289, 2024).
lipoblastoma (continued). "Taken together, these observations suggest that the oncogenic activities of PLAG1 is at least partly mediated by IGF2 signaling and that IGF2 signaling is a potential therapeutic target in pleomorphic adenoma and hepatoblastoma and possibly also in lipoblastoma." (PMID 31426421, 2019). "In addition, lipoblastoma demonstrates polysomy for chromosome 8 with or without PLAG1 rearrangement." (PMID 26943407, 2015). "Although FISH analysis of PLAG1 rearrangement in lipoblastoma does not show high sensitivity, combined analysis of both IHC and cytogenetic study may increase the diagnostic accuracy of lipoblastoma with unusual histology." (PMID 26943407, 2015). "Although PLAG1 immunopositivity can be observed in some cases of LLT, it is not exclusive to lipoblastoma." (PMID 41246635, 2025). "At the molecular level, they are characterized by the absence of PLAG1 and HMGA2 expression and by the lack of DDIT3 rearrangements, as detected by fluorescence in situ hybridization (FISH), which distinguishes them from lipoblastomas and myxoid liposarcomas." (PMID 41246635, 2025).
adenoma (14 papers, 2006 to 2026). A neoplasm arising from the epithelium. "In PLAG1 overexpressed mice which promoted adenomas occurrence in salivary glands, simultaneous furin deficiency resulted in delayed tumorigenesis." (PMID 22808247, 2012). "In addition, in silico a loss of a pleomorphic adenoma gene 1 (PLAG1) transcription factor binding site was predicted." (PMID 33036198, 2020). "Immunohistochemical findings showed nuclear positivity for a murine double minute 2 (MDM2) and cyclin-dependent kinase 4 (CDK4) and negativity for pleomorphic adenoma gene 1 (PLAG1)." (PMID 39109289, 2024). "PLAG1 (pleiomorphic adenoma gene 1) overexpression was first observed in pleiomorphic adenomas of the salivary glands, identifying PLAG1 as an oncogene." (PMID 35741015, 2022). "Another interesting gene in this interval is PLAG1 (pleomorphic adenoma gene 1) for which chromosomal aberrations have been described that lead to over-expression in salivary gland tumors." (PMID 16982006, 2006). "For the opposite case, u(MA, HA), the gene DSPP, related to deafness and tooth abnormalities (dentin dysplasia and dentinogenesis imperfecta) were found alongside PLAG1, DCLRE1C and PLCB2 to be associated with adenomas, severe immunodeficiency and platelet deficiency respectively." (PMID 29161290, 2017). "In human, PLAG1 is related to the pleiomorphic adenoma gene and regulates human height." (PMID 27997562, 2016). "In these mice, the simultaneous inactivation of furin and overexpression of the PLAG1 transcription factor, which induced the formation of adenomas in salivary glands, showed that the absence of furin delayed tumorigenesis, suggesting a pro-tumorigenic effect of furin." (PMID 19737405, 2009).
pleomorphic adenomas of the salivary gland (12 papers, 2013 to 2023). "PLAG1, located on chromosome 8q12, is mostly mutated in pleomorphic adenoma of the salivary gland." (PMID 36600208, 2023). "The most common chromosomal rearrangements in pleomorphic adenomas of the salivary gland involve 8q12, containing the target gene PLAG1, or 12q13-15 with the target gene HMGA." (PMID 37250610, 2023). "PLAG1 is a known oncogene first identified in pleomorphic adenomas of the salivary gland, and later found to be upregulated in CLL due to deregulation of repressive miRNAs." (PMID 33544756, 2021). "Ectopic overexpression of PLAG1 has been proposed to play a crucial role in tumorigenesis of salivary gland pleomorphic adenomas." (PMID 30221000, 2018). "PLAG1 is a proto-oncogene whose overexpression is a crucial oncogenic event in salivary gland pleomorphic adenomas (PA), and in carcinoma ex pleomorphic adenoma (CA-ex-PA)." (PMID 30221000, 2018). "Plag1 is a proto-oncogene that is often up-regulated in pleomorphic adenomas of the salivary glands, a cancer that makes up 70% of parotid tumors." (PMID 25928148, 2015). "In pleomorphic adenomas of the salivary glands (PASG) recurrent chromosomal rearrangements affecting either 8q12 or 12q14∼15 lead to an overexpression of the genes of the genuine transcription factor PLAG1 or the architectural transcription factor HMGA2, respectively." (PMID 24516594, 2014).
hepatoblastoma (9 papers, 2013 to 2025). Hepatoblastoma (HB) is a malignant hepatic tumor and is the most common pediatric liver cancer. "In addition, PLAG1 is amplified and overexpressed in hepatoblastomas associated with poor prognosis." (PMID 31426421, 2019). "Recent report illustrated the over-expression of PLAG1 in hepatoblastoma, suggesting a potential role of PLAG1 in liver malignant disease." (PMID 25060425, 2014). "Recent report indicates that PLAG1 might be involved in regulatory gene work of hepatoblastoma, malignant liver tumor commonly occurred in childhood, suggesting a potential role of PLAG1 in malignant liver diseases." (PMID 25060425, 2014). "PLAG1 was first isolated from salivary gland adenomas, while PLAGL2 was isolated in hepatoblastomas." (PMID 37371750, 2023). "The finding that PLAG1 is overexpressed and induces IGF2-p3 activation also in hepatoblastoma cell lines suggests that PLAG1 and PLAGL2 may play a wider role in IGF2 overexpression in cancer." (PMID 37371750, 2023).
salivary gland tumors (9 papers, 2006 to 2025). "The LCORL protein is a transcription factor implicated in humans in effects on skeletal size and adult height; PLAG1 is developmentally regulated, often associated with salivary gland neoplasms, and has been linked with growth rates in cattle." (PMID 28219344, 2017). "Various studies including ours verified that Plag1 transgenic mice spontaneously developed salivary gland tumors with similar histopathological features to human pleomorphic adenomas." (PMID 21858056, 2011). "We found that salivary gland tumors induced by Plag1 overexpression contained CD44hi cells that incorporated BrdU at a low cycle rate and retained BrdU better than CD44neg cells; and that CD44hi cells have higher levels of transcripts of stem cell related genes, Oct-4, Nanog, Sox2 and telomerase." (PMID 21858056, 2011). "The first FGFR fusion observed in epithelial cancers, FGFR1-PLAG1, was found in a subset of pleomorphic salivary gland adenomas, and involves FGFR1 as the 5′ partner upstream of PLAG1, the known driver of salivary gland tumors." (PMID 26684754, 2015). "Despite the efficacy of PLAG1 and HMGA2 testing in the diagnosis of pleomorphic adenoma, especially in an unusual site such as the kidney, in the absence of a prior history of salivary gland neoplasm, we did not perform these stains as we do not carry stains for PLAG1 and HMGA2." (PMID 41268216, 2025).